IL33 (interleukin 33)
Diseases named in the same sentence as IL33 in open-access papers (continued):
Sharing a sentence is not in itself a finding about the gene and the disease.
allergic disease (continued). "In conclusion, we have uncovered a novel mechanism by which pollen/TLR4 innate immunity signaling initiates IL-33/ST2 allergic pathway that triggers Th2-dominant inflammation in pollen induced allergic diseases." (PMID 27796360, 2016). "In this review, we summarize the current knowledge regarding the roles of IL-33 and mast cells in the pathogenesis of allergies and inflammation." (PMID 26425339, 2015). "According to a great deal of recent reports, IL-33 plays a crucially important role for developing allergic diseases 30,31." (PMID 26417444, 2015). "TSLP and IL-33 have recently been recognized for their etiologic role in atopic dermatitis, the earliest manifestation of childhood allergy." (PMID 26084354, 2015). "Future studies are essential to recognize the biological and clinical significance of IL-33 in allergic diseases." (PMID 26425339, 2015). "The present study investigated for the first time the relationship between IL-31, IL-33, and 25(OH) Vit D in pediatric allergic disease of the airways." (PMID 25061262, 2014). "IL-33 is a prime candidate in the development of allergy as it clearly promotes Th2 (as well as ILC2) responses." (PMID 24409181, 2013). "By promoting Th2 type immune response, IL-33 plays important roles in the allergy, whereas its function in autoimmune diseases attracts more attention." (PMID 24151520, 2013). "Very recent and complementary experiments using the same HDM allergy mouse model elucidated the mechanism leading to GM-CSF and IL-33 following TLR4 signaling in bronchial epithelial cells." (PMID 23724247, 2013). "Given that some allergens can directly induce tissue damage along with previous implications of IL-1 and IL-33 in Th2-mediated inflammatory responses, the prediction that NLRs play a role in the development of allergic diseases seems obvious." (PMID 24409181, 2013). "IL-33 plays a major role in Th2 responses by inducing Th2 cytokines IL-4, IL-5, IL-13, splenomegaly, eosinophilia, and allergy." (PMID 23112799, 2012). "The role of IL-33 has been shown in some allergic diseases, such as anaphylactic shock, atopic dermatitis or bronchial asthma." (PMID 22349136, 2012). "In the present study we found that a serum level of IL-33 is a marker of Th2-mediated allergic diseases, such as intermittent allergic rhinitis and, moreover, IL-33 is a marker of the intermittent allergic rhinitis severity." (PMID 22349136, 2012). "The alarmins, IL-25, IL-33, and TSLP activate ILC2s and are linked to allergic diseases." (PMID 41915169, 2026). "Despite growing interest in the role of alarmins, such as TSLP, IL-25, IL-33 and periostin, in allergic diseases, most existing data have been acquired from studies of adults or eosinophilic esophagitis, and little is known of their activity in children with GERD." (PMID 40981017, 2025). "Indeed, IL-1R8 is involved in tuning IL-33-dependent Th2 responses in allergies, IL-1-induced Th17 activation in autoimmunity, and IL-18-induced Th1 responses and NK cell antitumoral and antiviral functional activation." (PMID 41087719, 2025). "Indeed, during allergy and anti-helminth immunity, epithelial cells of damaged barriers release alarmins including IL-25, IL-33, and thymic stromal lymphopoietin (TSLP), but also chemokines such as CXCL1 and CCL11, to promote cell recruitment and inflammation." (PMID 40943268, 2025). "IL-33 was shown to enhance the production of IgE in allergic diseases." (PMID 38787044, 2024). "Furthermore, the activated NLRP3 inflammasome promotes the expression and regulation of various inflammatory factors, including IL-6, IL-17, and IL-33, participating in allergic disease development." (PMID 39131161, 2024). "Likewise, IL-33-positive cells, such as macrophages, MCs, endothelial cells, and fibroblasts, are also significantly increased in the dermis of CSU skin lesions, while IL-33 plays an important role in type 2 immunity and allergic diseases." (PMID 38380314, 2024).
allergic disease (continued). "Discrepancies in the results of IL-33 concentration measurements across various studies may arise due to the influence of other non-allergic diseases in patients." (PMID 38731070, 2024). "IL-33 also contributes to the exacerbation of inflammation in allergic diseases by activating eosinophils, basophils, and mast cells; IL-33 potently induces eosinophilia, produces superoxide, upregulates the expression of adhesion molecules, and enhances cell survival." (PMID 37834081, 2023). "IL-33 has been indicated to play an important role in allergic diseases." (PMID 37545493, 2023). "Mast cell-derived IL-10 has been shown to alleviated severe cutaneous contact hypersensitivity reactions, and IL-33, an alarming signal in the allergic diseases and inflammation, could activate mast cells and trigger downstream reactions." (PMID 38012745, 2023). "In addition to such allergic reactions, we suggest that the co-sensing of ATP and IL-33 by MCs also contributes to the development of pulmonary diseases such as COVID-19." (PMID 38067124, 2023). "We speculate that ATP/IL-33 co-sensing by MCs is not limited to allergies but also plays an important role in infectious diseases such as COVID-19, which is characterized by a massive destruction of lung tissues." (PMID 38067124, 2023). "IL-33 might be a potential target to assess the development of DEHP-related childhood allergic disease." (PMID 37545493, 2023). "The present study indicated that IL-33 might be a potential target to assess the development of prenatal DEHP exposure-related childhood allergy." (PMID 37545493, 2023). "Additionally, IL-33 promoted a significant release of the pro-inflammatory cytokine IL-6 and chemokines CXCL8 and CCL2 from eosinophils, indicating that IL-33 plays a crucial role in promoting inflammation in allergic diseases." (PMID 38082335, 2023). "It was found that IL-33 could be released after stress and infection, which played an important role in an allergic reaction, inflammation, autoimmune disease, and host defense." (PMID 35096114, 2022). "Thus, the effect of a “surge” IL-33 release from cells is best understood in conditions of allergy, necrosis, or mechanical injury." (PMID 34531552, 2022). "Moreover, also in atopic dermatitis, an inflammatory allergic disease, there is an increase in IL-33 compared to healthy subjects." (PMID 36362030, 2022). "Therefore, the investigation of IL-33-induced signaling is of interest for developing therapeutic interventions effective against allergic reactions." (PMID 36142767, 2022). "In the case of allergy, one example is the “ARI” (alarmin release inhibitor), a 20-kDa protein in the excretory/secretory (ES) products of the intestinal nematode Heligmosomoides polygyrus that blocks release of IL-33, a central player in both allergy and helminth immunity." (PMID 35353624, 2022). "Moreover, considering that mast cell proteases can cleave full-length IL-33 to a more active IL-33 domain, they can become a potential therapeutic target for IL-33-mediated allergic diseases." (PMID 36498859, 2022). "The cytokine IL-17E can act independently of IL-33 in the production of the allergic response." (PMID 34829186, 2021). "It has also been proposed that IL-33 could be degraded by some mast cell proteases to limit inflammation during allergic reaction." (PMID 35011670, 2021). "Recognizing the significant effect of TSLP, IL-25 and IL-33 on the pathogenesis and development of allergic diseases and the effect of elevated concentrations of these alarmins on the number of allergen components to which the patient was sensitized was analyzed in the ImmunoCap ISAC test." (PMID 34301307, 2021). "Hence, IL-33 has been involved in different immune processes, such as inflammatory diseases, allergies, infections and cancer." (PMID 33329534, 2020).
allergic disease (continued). "The data presented herein provides evidence to support the conclusion that inducible IL-33 from hematopoietic cells does play functional roles in allergic disease pathogenesis and offer a deeper understanding for how such sources of IL-33 influence inflammation." (PMID 31940364, 2020). "Taken together, targeting IL‐33 remains a therapeutic option for dysfunction and allergic disease." (PMID 32566227, 2020). "Importantly, release of IL-33 is ROS-regulated by NADPH oxidase dual oxidase 1 (DUOX1) whose activity is elevated in allergic disease." (PMID 33424827, 2020). "This novel cross-regulation may explain exacerbated complement- and MC-dependent Th2 responses and thus provides an additional rationale for targeting anti-IL33 therapeutically in allergic diseases." (PMID 33597949, 2020). "Recently was suggested that the IL-31/IL-33 axis could be involved in different conditions such as cancer, autoimmune diseases and allergies." (PMID 31973226, 2020). "This newly identified cross-regulation may be important for controlling exacerbated complement- and mast cell-dependent Th2 responses and thus provides an additional rationale for targeting anti-IL33 therapeutically in allergic diseases." (PMID 33597949, 2020). "CLOCK temporally gates the mast cell and basophil response to IL-33 via regulation of ST2 expression, which may also underlie circadian nature of allergic disease." (PMID 32595651, 2020). "Based on these considerations, a potential complex interaction between vitamin D and IL-33 has been hypothesized, not only in allergic diseases but also in other clinical conditions in which their roles have also been demonstrated, including Pso and OP." (PMID 33488605, 2020). "In allergic disease, epithelial barrier disruption leads to production of innate cytokines such as IL-33 that skew DC phenotypes and activate innate immune cells (e.g., ILC2s, mast cells, and basophils), thereby eventually promoting the development of Th2 cell that secrete IL-4, IL-5, and IL-13." (PMID 32595651, 2020). "Proteases play important role in IL-33-mediated allergic diseases." (PMID 30886621, 2019). "It becomes a potential therapeutic target for IL-33 mediated allergic diseases." (PMID 30886621, 2019). "IL-33 also regulates other allergic diseases, including atopic dermatitis." (PMID 31509992, 2019). "As an initiator, director, and maintainer of allergic inflammation, ATP triggers the release of IL-33 and activates dendritic cells to programme allergic responses, while in established allergy it augments IgE-dependent mediator release from mast cells and provokes dyspnoea." (PMID 30423826, 2018). "IL-33 is now thought to play a significant role in mast cell-associated diseases such allergy, although precise mast cell-restricted functions are not clear and remain to be elucidated." (PMID 29755466, 2018). "The same results were also depicted in EAE and allergy mice treated with IL-33." (PMID 28423665, 2017). "IL-33 is a critical mediator in allergic disease and an important clinical target." (PMID 29045903, 2017). "In particular, we focus on the accumulating evidence for a role of IL-33 in regulating hematopoiesis and how this relates to eosinophils as well as how this may provide new concepts for how the progression of allergy is regulated." (PMID 28512632, 2017). "Of these three cytokines, IL-33 has proven particularly interesting because of the strong associations found between both it and its receptor, ST2, in several genome-wide association studies of allergic diseases." (PMID 28512632, 2017). "Although TSLP, IL-25, and IL-33 have all been shown the contribute to the induction of Th2 responses, there seems to be a division of labour where each of the mediators can have a more prominent role depending on the allergy model under investigation." (PMID 27050744, 2016). "Recent research suggests that IL-33 plays an important role in allergy and inflammation." (PMID 26425339, 2015).
allergic disease (continued). "Thus, IL-33, IL-25 and TSLP are considered to be involved in host defense against nematodes and development of Th2-associated disorders, such as allergy." (PMID 24205109, 2013). "This concept suggests that IL-33 may represent a novel therapeutic target for a range of allergic diseases." (PMID 22702477, 2012). "Thus, the higher levels of IL-4, IL-10 and IL-33 found in DK may reflect the higher prevalence of allergies typically seen in high-income countries (HIC) compared to low- and middle-income countries (LMIC)." (PMID 40338935, 2025). "Thus, IL-33 participates in both innate- and acquired-type allergies." (PMID 38674885, 2024). "Inhibiting the IL-33 signaling pathway may be a new target for treating allergic diseases." (PMID 38082335, 2023). "Thus, IL-33 may promote both food allergy symptoms in the intestine and food-induced anaphylaxis and conversely blocking of IL-33 signaling has been shown to inhibit anaphylactic reaction after oral challenge." (PMID 36904070, 2023). "Importantly, phase 2a randomized placebo-controlled study of anti-IL-33 in peanut-induced allergy suggests that a single dose of Etokimab, IL-33 blocker, could reduce atopy-related adverse effecs." (PMID 34084159, 2021). "However, while a reduction of IL-33 may be beneficial in allergic diseases, perhaps neutralizing IL-33 disrupts early anti-viral events needed to control the viral infection." (PMID 34266437, 2021). "Furthermore, recent reports showed that air pollutants, cold exposure and exercise also induce IL-33 production, suggesting the involvement of ILC2s in allergies caused by these non-antigenic factors." (PMID 34498700, 2021). "Ideally, one might use humanized mice in which the murine IL-33 gene has been replaced by the human IL-33 gene, which would allow to test the effect of human IL-33trap in an allergic disease mouse model that relies on human IL-33 production from epithelial or endothelial cells." (PMID 32754154, 2020). "Moreover, the anti-IL-33 or anti-ST2 strategy may hold a potential clinical future outside the field of respiratory diseases with allergy or atopic dermatitis as examples." (PMID 32582171, 2020). "Therefore, IL-33-blocking agents may be a novel therapeutic modality to treat allergic diseases and some promising compounds have recently been developed." (PMID 30886621, 2019). "Thus, this led to the newest theory of an “IL-31/IL-33 axis” that could be involved in several conditions such as allergies, autoimmune-diseases, and cancer." (PMID 31766607, 2019). "In the early stage of allergy and tissue injury, up-regulated IL-33 in response to stimulator is necessary for the reduction of tissue integrity damage via ST2 expressed in ILC2s, suggesting IL-33 and ILC2s may be critical for maintaining epithelial integrity and tissue homeostasis." (PMID 29987222, 2018). "Finally, as a corollary parallel analysis showed that administration of rLc-IL12 suppressed allergic reaction without downregulating levels of IEC-derived IL-33 while at the same time partially suppressing allergy-associated expression of OX40L." (PMID 29896198, 2018). "Therefore, the IL-33/Bcl6 axis might participate in allergy pathology via the regulation of Il4 in MPT cells to promote disease development in MPTH2 and NAMTH2 cells, contributing to the maintenance and exacerbation of disease pathology." (PMID 29696026, 2018). "We hypothesized that AS-IV exerts its anti-allergy effects by regulating the production of key pro-allergic cytokines based on the fact that interleukin (IL)-33 and thymic stromal lymphopoietin (TSLP) levels increase significantly in the initial stage of the sensitization phase." (PMID 27917896, 2016). "In allergy-related cytokines, Fat only led to significant increases in multiple BALF cytokines, notably IL-4, IL-5, IL-6, IL-12, IL-13, IL-17, IL-33, TNF-α, and IFN-γ, compared to the normal chow group (NC) (all P < 0.05 or P < 0.01)." (PMID 40998975, 2025).
allergic disease (continued). "The epithelial cell-derived cytokines IL-25 and IL-33 can potentiate type-2 immune responses by activating both ILC2 and Th2 cells in allergy and helminth infection." (PMID 37337050, 2023). "The IL-33/ST2 axis plays a crucial role in myriad conditions, extending beyond allergies to span obesity, Alzheimer’s disease, and cancer." (PMID 37762328, 2023). "Therefore, IL-33 inhibitors might serve as a potential breakthrough in relieving allergic diseases." (PMID 37686309, 2023). "At present, several monoclonal antibodies against IL-33 or ST2 are still under development and are currently being tested in phase I and II clinical trials, mainly for the treatment of patients with allergic diseases." (PMID 35328556, 2022). "Innate cytokines including the alarmins IL-25, IL-33, and TSLP are produced by epithelial cells and are key mediators of allergic disease." (PMID 33717078, 2021). "The role of IL-33/ST2 signaling has been widely investigated in various pathological conditions, including infection and allergic diseases." (PMID 34209038, 2021). "Recent identification of memory Th2 cells with high expression of receptors for IL-25, IL-33, and TSLP supports a role of these cytokines in adaptive immune responses in allergy." (PMID 33945508, 2021). "Biologics targeting upstream cytokines, such as IL-33 and TSLP, are highly anticipated for allergy treatment." (PMID 32066836, 2020). "Clinical studies find that IL-33 and ST2 expression are often increased in biological fluids or tissue specimens from patients with allergic diseases." (PMID 32903501, 2020). "Cytokine traps targeting IL-33, TSLP, IL-4 and IL-13 are novel tools that nicely complement the use of monoclonal antibodies for the treatment of allergic diseases." (PMID 32754154, 2020). "Because IgE- and IL-33-mediated mast cell activation plays a key role in the development and maintenance of allergic diseases, synthetic compounds capable of modifying the period, phase, or amplitude of clock gene expression in mast cells may have potential as new anti-allergy drugs." (PMID 31847374, 2019). "Recently, we reported that a TH2-promoting factor, namely, IL-33-mediated breakdown of Bcl6 in NAMTH2 cells, is likely involved in allergies given the effect of IL-33 on both MPT and NAMTH2 cells." (PMID 29696026, 2018). "ILC2s and many positive regulators including CysLTs, PGD2, IL-33 and TSLP are elevated in the airways of patients with allergic diseases, which supports an environment of ILC2-driven inflammation." (PMID 28959799, 2017). "In addition to therapeutic targeting of TSLP and IL33, local application of non-pathogenic LPS may be a rational strategy to prevent allergies." (PMID 27826297, 2016). "IL33 is a member of the IL1 family of cytokines and has been identified as an important factor in allergic diseases." (PMID 24465642, 2014). "Thus one can assume that IL-33 may be a potential therapeutic target against allergy in humans too." (PMID 22349136, 2012). "However, IL-33 activates ILC2 cells, which, at the pathophysiological level, drive some human disorders, such as inflammation in asthma, allergy, atopic dermatitis, and fibrotic diseases." (PMID 41596472, 2026). "Studies show that the IL-33/ST2 axis drives the activation and proliferation of immune cells by activating the PI3K/AKT pathway, thereby playing a role in various diseases such as autoimmune disorders, allergic reactions, and tumorigenesis 75-76." (PMID 41362726, 2026). "Moreover, house dust mites in AD patients with house dust mite allergy and patients exposed to staphylococcal enterotoxin B had an increased expression of ST2 and IL-33 mRNA in the skin over time." (PMID 41155460, 2025). "The concentrations of maternal urinary DEHP metabolites and serum IL-33 in cord blood with childhood allergy were significantly higher than those in the non-childhood allergy group." (PMID 37545493, 2023).